TNF (tumor necrosis factor)
Diseases named in the same sentence as TNF in open-access papers (continued):
Sharing a sentence is not in itself a finding about the gene and the disease.
autoimmune disease (continued). "TNF holds the central place in the pathogenesis of many autoimmune diseases, and its participation in the process leading to RA is well documented." (PMID 32111105, 2020). "Mutations in the SAMHD1 gene are associated with an autoimmune disorder through the irregular response of type I IFN, which characterizes Aicardi-Goutières syndrome, in which there is marked production of IL-12 and TNF-α." (PMID 32656092, 2020). "TNF-α is located in the HLA-DR/DP locus; therefore, its appearance in GWAS studies of autoimmune diseases is unsurprising." (PMID 32793226, 2020). "TNFα is an inflammatory cytokine that is dysregulated in many autoimmune diseases and is generally found at increased levels in disease-relevant tissues." (PMID 32231389, 2020). "An increase in tumor necrosis factor-alpha (TNFa) levels as a result of infection or some autoimmune diseases can trigger this process." (PMID 32231389, 2020). "Among the pro-inflammatory cytokines, studies have focused on the role of TNF-α in autoimmune diseases: anti-TNF-α therapy remarkably decreases the clinical manifestation of diseases associated with inflammation." (PMID 32357539, 2020). "On the one hand, they are responsible for autoimmune disorders that involve inflammation and tissue injury; on the other hand, they can kill tumor cells in the same way as do TNFα and the Tag7–Hsp70 complex, thereby showing an antitumor activity." (PMID 32636466, 2020). "These TNFα blocking agents have long been used in the clinical setting to treat inflammatory and autoimmune diseases." (PMID 32391269, 2020). "Paradoxical inflammatory effects of TNF-α inhibitors have also been noted and include exacerbation or initiation of drug-induced autoimmune diseases, such as psoriasis, systemic lupus erythematosus, vasculitis, and uveitis." (PMID 32337619, 2020). "We analyzed a cohort of 305 ME/CFS patients and 201 healthy controls for potential disease association of the PTPN22, CTLA4, TNF, and IRF5 SNPs that were described to be risk loci for various autoimmune diseases." (PMID 32328064, 2020). "TNF-α is produced primarily by monocytic lineage cells, such as macrophages and TNF-α-activated macrophages, which can cause many autoimmune diseases." (PMID 33265935, 2020). "Various studies have established AA as a T-cell-mediated autoimmune disease and multiple cytokines, especially the helper T-cell type 1 cytokines such as TNF-α, are required for the inflammation process." (PMID 32411613, 2020). "This wide cellular expression in the immune system makes TNF a crucial regulator of autoimmune responses, which explains the development of a plethora of anti-TNF drugs for autoimmune disorders (see later paragraph 4)." (PMID 33066433, 2020). "Anti-TNF-α therapeutic approaches currently used in autoimmune diseases have been proposed as a therapeutic strategy in AD." (PMID 32457323, 2020). "Tumor necrosis factor-alpha (TNF-α), checkpoint inhibitors, and interleukin-17 (IL-17) are critical targets ininflammation and autoimmune diseases." (PMID 31376325, 2020). "A number of studies have shown that TNF-α also has an anti-inflammatory effect in limiting inflammation in vivo and autoimmune diseases." (PMID 32210942, 2020). "IFN-γ, TNF-α and IL-1β have long been recognized as signature pro-inflammatory cytokines that play a central role in inflammation and autoimmune diseases, high levels are positively correlated with disease outbreak." (PMID 32244599, 2020). "TNF-α is a major pro-inflammatory cytokine that has been identified as a key molecule involved in autoimmune diseases as RA and neurodegenerative diseases as AD6." (PMID 32457323, 2020). "Studies on the inflammatory activity of TNF have been translated into clinical success, namely blocking antibodies used to suppress autoimmune diseases." (PMID 31916677, 2020).
autoimmune disease (continued). "MMP-1 expression is augmented in inflammatory and autoimmune diseases through upregulation by inflammatory cytokines such as TNF α (tumor necrosis factor-α) and IL-1 (interleukin-1)." (PMID 32486345, 2020). "Inhibition of TNF-α has emerged as a potential therapeutic to treat tumor and especially autoimmune diseases." (PMID 33262408, 2020). "TNF-α is another cytokine that plays an important role in the regulation of inflammatory response in many autoimmune diseases by T cells activation and apoptosis induction." (PMID 32012782, 2020). "Another cytokine that plays an important role as an intermediary molecule in autoimmune diseases is tumor necrosis factor α (TNF-α)." (PMID 31561568, 2019). "Tumor necrosis factor alpha (TNF-α) is a pro-inflammatory cytokine, and its abnormal over-expression causes many inflammatory or autoimmune diseases." (PMID 31089365, 2019). "The ambivalence of therapeutically targeting TNF is emphasized by the experience with TNF inhibitors in the treatment of autoimmune diseases." (PMID 31555271, 2019). "From the autoimmune disease (AD) subsets that entail the multiple inflammatory cascades, one of the most significant players is the TNF-α, particularly the over-expression of the TNF-α." (PMID 30965588, 2019). "Although significant efficacy of anti-TNF has been reported, side effects of TNF-α inhibition such as infection, malignant tumor, autoimmune disease, and demyelinating disease have been reported." (PMID 31620105, 2019). "Anti-TNF-α therapy for autoimmune diseases resulted in a significant improvement in the fasting blood glucose, glycated hemoglobin, and triglyceride values of such patients." (PMID 30915358, 2019). "Increasing evidence suggests that thymus-derived, natural regulatory T cells (nTreg) express a remarkably high level of TNF Receptor 2 (TNFR2) and TNFα modulates the number or function of nTreg via TNFR2 in autoimmune diseases." (PMID 30631042, 2019). "It has been well recognized that TNF-α is critically involved in the pathogenesis of RA and many other autoimmune diseases, however, its effect on Treg biological activity has been controversial." (PMID 30990587, 2019). "As TNF-α antagonists have already been used to treat a number of neurodegenerative and autoimmune diseases, clinical trials would be worthwhile for this potential treatment for WMI in preterm infants." (PMID 31470812, 2019). "Dysregulation of TNF-α can be a factor in autoimmune disease and anti-TNF antibodies are used to treat a range of inflammatory disorders." (PMID 31263060, 2019). "Due to the use of biological agents, particularly TNF-α inhibitors, as a well-established therapy for some autoimmune diseases, new potential adverse events can be expected in the future and we wanted to point out one of them." (PMID 30732563, 2019). "One autoimmune disease where TNF plays a pivotal role is multiple sclerosis (MS) - a chronic inflammatory disease of the central nervous system (CNS), with a strong autoimmune inflammatory component accompanied by neurodegeneration." (PMID 30206422, 2018). "A recent evidence indicates that TNF-α plays a vital role in the regulation of Th17 cells and Tregs in some inflammatory and autoimmune diseases and tumors." (PMID 29922294, 2018). "In vivo studies suggest that OSM has anti-inflammatory effects mediated by inhibition of IL-1 and TNF-α responses, and it seems to suppress inflammation in animal models of autoimmune diseases." (PMID 30249022, 2018). "They represent the unexpected onset or exacerbation of an autoimmune disease for which TNF blockers are indicated other than the one the patient is treated for." (PMID 29751683, 2018). "Upregulation of the expression of tumor necrosis factor (TNF-α, TNF) has a significant role in the development of autoimmune diseases." (PMID 31544893, 2018). "TNF-α is an important cytokine and a vital mediator of inflammation, infection, and autoimmune disease." (PMID 29867985, 2018).
autoimmune disease (continued). "Five anti-TNF drugs are currently approved for the therapy of human autoimmune disorders: RA, plaque psoriasis, psoriatic arthritis, AS, and IBD." (PMID 29725328, 2018). "Despite the wide use of TNF inhibitors, drawbacks include severe side effects like opportunistic infections, reactivation of tuberculosis, and even development of autoimmune diseases, lymphoma, and many other cancers." (PMID 29725328, 2018). "Infliximab (Remicade) is a therapeutic chimeric mAb against TNF used in the treatment of autoimmune diseases." (PMID 29632537, 2018). "It is well accepted that TNF-α plays a critical role in various autoimmune diseases including RA, and various neutralizing TNF-α monoclonal antibodies and soluble receptors have been successfully used clinically to treat RA." (PMID 29850502, 2018). "Tumor necrosis factor (TNF or TNFα), which is involved in a wide range of biological functions, is considered the master mediator of the pathogenesis of chronic inflammation and autoimmune diseases." (PMID 30079066, 2018). "Although, Anti-TNF biologics have revolutionized the treatment of these autoimmune diseases, formation of anti-drug antibodies (ADA) has dramatically affected their use." (PMID 29881431, 2018). "Case series have reported the development of sarcoidosis after the administration of TNF-alpha inhibitors for other autoimmune disorders." (PMID 30064495, 2018). "Tumor necrosis factor α (TNFα) drives the pathophysiology of human autoimmune diseases and consequently, neutralizing antibodies (Abs) or Ab-derived molecules directed against TNFα are essential therapeutics." (PMID 30108591, 2018). "During RA and other autoimmune diseases, pro-inflammatory cytokines such as IL-1 and TNF-α alter this subtle equilibrium in favor of bone-resorptive mechanisms, ultimately leading to local (bony erosions) and systemic (osteoporosis) consequences." (PMID 29915588, 2018). "Etanercept is a competitive TNF inhibitor, and is widely used in clinical treatment to cure autoimmune diseases." (PMID 30519229, 2018). "A long standing class of biologics used for many autoimmune diseases is TNF blockers which includes infliximab, etanercept, adalimumab, PEGylated certolizumab, and golimumab." (PMID 29760711, 2018). "The block of the TNF-α signalling has been a target to treat various inflammatory diseases and successfully used in the case of autoimmune diseases such as rheumatoid arthritis, Crohn’s disease, and psoriasis." (PMID 30563131, 2018). "Although partially effective in other autoimmune diseases, anti-TNF therapies in MS patients seem to worsen pathology and clinical symptoms." (PMID 29760711, 2018). "Together, these findings suggest that TNF signaling plays a pivotal role in MSC-based therapy of autoimmune disease, which is highly dependent on the context, timing, concentration, gender, etc." (PMID 30079066, 2018). "We reasoned that the genetic susceptibility to TB is important not only for the general population but also for the patients with autoimmune diseases under immunosuppressive treatments such as treatment with anti-TNFα or anti-IL6 antibodies." (PMID 29888256, 2018). "Anti-TNFα drug molecules have shown the positive efficacy against IBD; in fact, TNFα is one of the dominant pro-inflammatory cytokines in autoimmune diseases." (PMID 29928282, 2018). "TNF and other pro-inflammatory cytokines, such as interferon γ (IFNγ) and interleukin 1 (IL-1), determine the disease onset, severity, and relapse of autoimmune diseases and affect the efficacy of treatment, including MSC-based therapy." (PMID 30079066, 2018). "Our data are in line with pre-clinical studies using etanercept (Enbrel®), a biopharmaceutical marketed to treat autoimmune diseases by acting as a TNF inhibitor." (PMID 29789012, 2018). "Tumor necrosis factor (TNF-α) inhibitory agents are increasingly being used in autoimmune diseases, such as IBD." (PMID 29850616, 2018).
autoimmune disease (continued). "In particular, TNF is abundant in the serum and many other body fluids in patients with autoimmune disease." (PMID 30079066, 2018). "The pro-inflammatory role of TNF in these autoimmune diseases is supported by the great clinical effects of TNF-antagonists, which are used in these disorders both in humans as well as in animal models of for instance RA." (PMID 29751683, 2018). "Pro-inflammatory cytokines such as TNF-α and IL-6 play crucial roles in the development of inflammatory diseases and are involved in immunity and autoimmune diseases." (PMID 29401674, 2018). "Tumor necrosis factor α (TNF) is a potent pro-inflammatory cytokine that has deleterious effect in some autoimmune diseases, which led to the use of anti-TNF drugs in some of these diseases." (PMID 29593717, 2018). "Of particular importance in several inflammatory and autoimmune diseases is the cytokine tumor necrosis factor-α (TNF-α) produced by activated monocytes and macrophages." (PMID 29540995, 2018). "As pro-inflammatory cells, Th17 cells can induce the occurrence of asthma and autoimmune diseases by secreting inflammatory factors such as IL-17A, IL-17F, IL-6 and tumor necrosis factor-α." (PMID 30089474, 2018). "TNFα is a Th1-related pro-inflammatory cytokine that is elevated in many autoimmune diseases, and its dysregulation characterizes many autoimmune diseases." (PMID 28946890, 2017). "Of relevance, two of these genetic patterns are significantly enriched in genes from immune response pathways that are crucial for this group of autoimmune diseases: TNFα and IFNγ cytokine pathways." (PMID 28982122, 2017). "A thorough multistep screening for Mtb is proposed for individuals who are subjected to anti-TNF therapy to treat autoimmune diseases." (PMID 28261197, 2017). "Overproduction of NO, TNF-α and IL-6 by macrophages leads to various pathological disorders such as carcinogenicity, cytotoxicity and autoimmune diseases." (PMID 27937124, 2017). "With great success in treating autoimmune diseases, anti-TNF biologics also represent the most profitable drug class in the history, exceeding $US 25 billion total sale in 2012." (PMID 28785220, 2017). "Two studies have shown the efficacy of anti-TNF therapy in treating amyloidosis secondary to autoimmune diseases, including JIA." (PMID 28499374, 2017). "Etanercept binds with and inhibits tumor necrosis factor (TNFα), which is a key immune system protein involved in a number of autoimmune diseases." (PMID 28819167, 2017). "In the clinical settings, TNF blockers such as infliximab, adalimumab, certolizumab pegol, and etanercept are routinely used for the treatment of various autoimmune disorders." (PMID 28261197, 2017). "Inhibition of the TNF has been achieved by the anti-TNF biologic etanercept, antibodies like infliximab and adalimumab, or with the antibody fragment certolizumab, used to treat autoimmune diseases." (PMID 28824615, 2017). "More recently, treatment for RA and other autoimmune diseases has been revolutionized with the discovery that TNF is critically important in the development of the diseases." (PMID 28785220, 2017). "Anti-TNF-α blockers have reshaped the treatment of rheumatoid and autoimmune diseases, being the most effective drugs in our therapeutic armentarium." (PMID 28337644, 2017). "Over the past decade, the concept of targeting cytokines to treat autoimmune diseases has evolved at a rapid pace, such as some medicines approved by the drug administration to target IL-1β, IL-5, IL-6, IL-2, TNF-α, and IFN-γ." (PMID 29250557, 2017). "This protease-supraparticle hybrid, in vitro allowed for systematic inactivation of the cytokine tumor necrosis factor-alpha (TNF-α), which is responsible for inflammatory effects potentially causing autoimmune diseases." (PMID 30920512, 2017).
autoimmune disease (continued). "The introduction of anti-TNF therapeutics has revolutionized the management of autoimmune diseases, such as RA, psoriatic arthritis (PsA), plaque psoriasis (PP), AS, CD and ulcerative colitis (UC)." (PMID 28785220, 2017). "B cells, identified by releasing IL-10, IL-35, and TGF-β, had been shown to limit inflammation, autoimmune disease, and tumor, while B cells, identified by secreting TNF-α, IL-6, and GM-CSF, had been shown to promote disease." (PMID 28831210, 2017). "Selective inhibitors targeting key molecules, including cyclooxygenase-2 inhibitors, CD20 monoclonal antibody, TNF-alpha inhibitors and so on, have serious adverse reactions in the treatment of autoimmune diseases." (PMID 29311935, 2017). "One important target in anti-cytokine therapy of autoimmune diseases is TNF, and many systemic anti-TNF biologics are approved for clinical use." (PMID 28919896, 2017). "Humira is a TNF-alpha inhibitor effective in a number of autoimmune diseases; therefore its adoption by RA is more biologically supported than by OA—hence, the delay in OA’s adoption." (PMID 27124390, 2016). "In autoimmune diseases such as RA, anti-TNF biologics are now routinely administered and improve life quality for many patients, and, in cancer, we have recently witnessed the success of combined anti-CTLA4 and anti-PD-L1/PD-1 in the treatment of melanoma." (PMID 26997761, 2016). "A pro-inflammatory role of TNF in CNS autoimmune disease is further supported by the observations that TNF blockade prior to disease onset prevents or ameliorates EAE." (PMID 26906225, 2016). "Recombinant monoclonal antibodies (mAbs) against tumor necrosis factor alpha are widely used in the biopharmaceutical therapy of autoimmune diseases." (PMID 27652157, 2016). "Currently, many inflammatory mediators secreted by M1 macrophages, like IL-1β, COX-2, IL-6, and especially TNFα, are already successful therapeutic targets in various autoimmune diseases." (PMID 28163705, 2016). "Anti-TNF-α monoclonal antibodies are a common treatment for autoimmune diseases (i.e., RA and IBD), suggesting that dysregulated PADs cause uncontrolled TNF-α signaling." (PMID 27150598, 2016). "As already discussed, TNF therapy has found only limited clinical application in cancer treatment, while anti-TNF therapy is widely used in the treatment of autoimmune diseases." (PMID 27148266, 2016). "Anti-tumor necrosis factor α (anti-TNF-α) agents have been widely used in the field of autoimmune diseases and have proved decisive efficacy and relative safety." (PMID 27840642, 2016). "Pharmacological blockers of TNF and IL-6 are widely used in the clinic for treatment of various autoimmune disorders." (PMID 27148266, 2016). "In autoimmune disease, therapies with some approved biologics, including TNF-α inhibitors, have been shown to increase Treg numbers or function." (PMID 26834751, 2016). "PsO is a chronic, inflammatory, T-cell-mediated autoimmune disease that results from activation of inflammatory cytokines (interferon gamma, TNFα, IL-12, IL-23) and presents with erythematous scaly plaques in 1% to 3% of Caucasians." (PMID 28492015, 2016). "Of note, antigen-specific regulatory T cells activated by therapeutics antagonizing TNF-α or GM-CSF have been shown play major immune suppressive roles in RA and other autoimmune diseases." (PMID 27658047, 2016). "TNF is involved in the pathogenesis of a range of diseases, including infectious and autoimmune diseases, and more recently, complications arising in immune-related adverse events as a consequence of immune check point inhibition." (PMID 26765224, 2016). "TNF-α is a major cytokine which stimulates the inflammatory response and leads to many autoimmune diseases and other clinical problems." (PMID 27151598, 2016). "On the other hand, TNF-α is a major pro-inflammatory cytokine, which plays relevant roles in pathogenesis of many autoimmune diseases and stimulates secretion of other inflammatory cytokines." (PMID 27483999, 2016).